CLU (clusterin)
Diseases named in the same sentence as CLU in open-access papers (continued):
Sharing a sentence is not in itself a finding about the gene and the disease.
coronary artery atherosclerosis (1 paper, 2019). "Clusterin expression in different tissues could exert different roles in coronary artery atherosclerosis." (PMID 31534454, 2019).
cortical atrophy (1 paper, 2014). "In this study we identified RANTES, NSE, and transthyretin, in addition to Clusterin, to be associated with cortical atrophy in the MCI group, with Clusterin showing the strongest correlation with all brain regions assessed." (PMID 25012867, 2014).
Creutzfeldt-Jakob disease (1 paper, 2023). "One protein that is said to play a role in the pathogenesis of AD and Creutzfeldt-Jakob disease is clusterin." (PMID 36672070, 2023).
delirium (1 paper, 2026). A disorder characterized by confusion; inattentiveness; disorientation; illusions; hallucinations; agitation; and in some instances autonomic nervous system overactivity. "With regard to delirium, protein expression of apolipoproteins including CLU and APOE were previously found to be downregulated in the CSF of people with delirium compared to those with mild AD63." (PMID 41286463, 2026). "In our proteomic analysis, CLU protein levels were also downregulated in the plasma of people with incident delirium, but not significantly (P > 0.05)." (PMID 41286463, 2026). "Four out of five of the lead replicated MTAG signals were also significant in the original delirium GWAMA, with rs2279590 (CLU gene) being marginally nonsignificant (P = 0.058)." (PMID 41286463, 2026).
Fanconi anemia (1 paper, 2021). Fanconi anemia (FA) is a hereditary DNA repair disorder characterized by progressive pancytopenia with bone marrow failure, variable congenital malformations and predisposition to develop hematological or solid tumors. "In contrast, CLU possessed negative associations with DNA damage repair, antigen-processing machinery, KEGG discovered histones, Fanconi anemia, cell cycle, DNA replication, nucleotide excision repair, homologous recombination, mismatch repair, and cell cycle regulators." (PMID 35083278, 2021).
fibrosarcoma (1 paper, 2020). A malignant mesenchymal fibroblastic neoplasm affecting the soft tissue and bone. "Likewise, an increased production of clusterin was demonstrated after the administration of elevated quantities of TNF in a fibrosarcoma cell line with a constitutively small expression of clusterin." (PMID 32455998, 2020).
fluorosis (1 paper, 2018). "The present study consistently demonstrates the decreased antioxidant effect induced by fluorosis, which is possibly related to the reduced clusterin expression." (PMID 29273675, 2018).
gastric adenocarcinoma (1 paper, 2017). "In gastric adenocarcinomas, clusterin mRNA expression was higher in diffuse tumors containing signet ring cells compared with diffuse tumors without signet ring cells, and clusterin seemed to be secreted by tumor cells." (PMID 28902909, 2017).
GH-cell adenomas (1 paper, 2011). "Although high PTTG levels are also observed in gonadotroph pituitary adenomas, unlike GH-cell adenomas, we now show that gonadotroph adenomas do not express p21, but abundantly express clusterin in a cell specific manner." (PMID 21464964, 2011).
Gliosis (1 paper, 2020). Gliosis is the focal proliferation of glial cells in the central nervous system. "Collectively, these results indicate that CLU overexpression is associated with reduction of both neuritic dystrophy and gliosis, which is accompanied by decrease in Aβ accumulation in APP/PS1AAV-CLU mice compared with APP/PS1AAV-GFP mice." (PMID 33246484, 2020).
gonadotroph adenomas (1 paper, 2011). "High clusterin levels were observed in the αGSU.PTTG pituitary gland and in LβT2 cells stably and transiently transfected with mPttg, suggesting that in human gonadotroph adenomas clusterin might be also induced by high PTTG levels." (PMID 21464964, 2011). "As high clusterin expression was observed in benign gonadotroph adenomas and in small slow-growing αGSU.PTTG pituitary tumors, and also in LβT2 cells overexpressing mPttg, we analyzed the effects of altering intracellular clusterin levels." (PMID 21464964, 2011).
head and neck squamous cell carcinoma (1 paper, 2023). A squamous cell carcinoma that arises from any of the following anatomic sites: lip and oral cavity, nasal cavity, paranasal sinuses, pharynx, larynx, and salivary glands. "In head and neck squamous cell carcinoma (HNSCC), the protein CLU is targeted by an overexpressed oncogenic microRNA called miRNA-21." (PMID 37685987, 2023).
hearing loss (1 paper, 2015). "Our study suggests that CLU may be a novel target for the treatment of sensorineural hearing loss." (PMID 25605314, 2015).
hemangioma (1 paper, 2007). A benign vascular lesion characterized by the formation of capillary-sized or cavernous vascular channels. "A similar response by clusterin after treatment with glucocorticoids was obtained on hemangioma in vitro." (PMID 18078515, 2007).
HIV-1 infection (1 paper, 2024). The type species of lentivirus and the etiologic agent of acquired immunodeficiency syndrome (AIDS). "Upregulated C1QA, CD163, and CXCL16 and downregulated LMNA and CLU were identified as age-associated genes tied to HIV-1 infection." (PMID 38399364, 2024).
Hodgkins lymphoma (1 paper, 2020). A heterogeneous group of malignant lymphoid neoplasms of B-cell origin characterized histologically by the presence of Hodgkin and Reed-Sternberg (HRS) cells in the vast majority of cases. "In addition, clusterin, which has been found to be induced by IFN-γ in Hodgkin’s lymphoma, is considered as an oxidative stress regulatory molecule preventing cell apoptosis, another potential role contributing to the FL niche development." (PMID 33028033, 2020).
Hyperoxaluria (1 paper, 2017). Increased excretion of oxalates in the urine. "Results of our present study show that OPN, MGP, Fetuin B, Fn1, CD 44, Clusterin, Bikunin/AMBP genes are upregulated during hyperoxaluria and further increased with crystal deposition." (PMID 29091707, 2017).
intrauterine growth restriction (1 paper, 2024). "Likewise, other studies have demonstrated that elevated levels of CLU are linked to intrauterine growth restriction and are markedly upregulated in women with severe PE." (PMID 39201423, 2024).
kidney transplant (1 paper, 2022). A surgical procedure in which one or both kidneys from a donor are implanted into a recipient. "The literature review presented here suggests that NGAL, KIM-1, CXCL-10, CysC, OPN, and CLU may become essential markers in predicting allogeneic kidney transplant rejection." (PMID 35669103, 2022).
large-cell NEC (1 paper, 2024).
Lassa fever (1 paper, 2021). A viral hemorrhagic fever that is caused by the Lassa virus, which is transmitted by contact with infected rodents; it is characterized by fever, headache, malaise, myalgia, and hearing loss. "Genes involved in extracellular matrix and cell-adhesion were also modulated, particularly during fatal Lassa fever (NID1, TIMP3, ITGA11, TGM2, MMP8/9, OLFM4, PCDH20, and CADM3), as well as some others involved in coagulation (SERPIN, TFPI2) and apoptosis (CLU, BCL2L14)." (PMID 33398113, 2021).
leptospirosis (1 paper, 2020). A contagious bacterial infection caused by spirochetes of the genus Leptospira. "Among urinary biomarkers, the level of urine clusterin (uCLU)/Cr (p < 0.05) was significantly higher in leptospirosis patients." (PMID 32610429, 2020).
lung squamous cell carcinoma (1 paper, 2017). "In the cohort of lung squamous cell carcinoma, we also do not find that the clusterin IHC intensity have significance difference malignance associate clinicopathological data." (PMID 28954633, 2017).
melanoma in situ (1 paper, 2016). "Finally, in patients with melanoma in situ that never develop metastasis, serum CLU, VN and DCD levels were similar to those in the controls and only the serum SSA and PG levels differed." (PMID 27216146, 2016).
mesothelioma (1 paper, 2025). A usually malignant and aggressive neoplasm of the mesothelium which is often associated with exposure to asbestos. "The medically significant thresholds for differentiating mesothelioma patients who developed AKI vs. those who did not develop AKI were 5.1-fold for urinary clusterin." (PMID 41010375, 2025).
morbid obesity (1 paper, 2021). An excess of body weight, normally defined as an individual with a body mass index greater than 35 or a body weight greater than one hundred percent of ideal body weight. "Clusterin levels were found to be higher in the plasma of patients with morbid obesity and uncontrollable food intake compared with those with better eating control." (PMID 33994910, 2021).
mucopolysaccharidosis (1 paper, 2016). A group of autosomal recessive or X-linked inherited lysosomal storage disorders affecting the metabolism of mucopolysaccharides, resulting in the accumulation of mucopolysaccharides in the body. "Clusterin gene overexpression (9-fold) and protein overexpression (1.3 to 1.62-fold) was confirmed and located specifically in arterial plaques of mucopolysaccharidosis-affected dogs and mice." (PMID 26986213, 2016).
mucopolysaccharidosis type I (1 paper, 2016). The most common type of mucopolysaccharidosis. "Expression of clusterin, a protein implicated in other etiologies of cardiovascular disease, was assessed in canine and murine mucopolysaccharidosis type I aortas via Western blot and in situ immunohistochemistry." (PMID 26986213, 2016).
mycosis fungoides (1 paper, 2014). Classical mycosis fungoides is the most common type of mycosis fungoides (MF), a form of cutaneous T-cell lymphoma, and is characterized by slow progression from patches to more infiltrated plaques and eventually to tumors. "They claimed that CLU expression could be used as a prognostic marker in early-stage mycosis fungoides to determine the progression to a poor prognosis." (PMID 24803721, 2014).
myelodysplastic syndrome (1 paper, 2022). A clonal hematopoietic disorder characterized by dysplasia and ineffective hematopoiesis in one or more of the hematopoietic cell lines. "This specific clusterin proteoform seems to be a promising biomarker for myelodysplastic syndrome progression." (PMID 35007303, 2022). "Moreover, there was a notable increase in the clusterin proteoform in the exosome-rich fraction of plasma of patients with more severe myelodysplastic syndrome; this corresponded with a simultaneous decrease in their plasma." (PMID 35007303, 2022).
myeloma (1 paper, 2023). "RNA-sequencing analysis suggested communication between RUNX2, M-CSF, ITGB3, CD44, LCN2, and CLU in RUNX2 k/in myeloma cells." (PMID 36897488, 2023).
Neurofibrillary tangles (1 paper, 2021). Pathological protein aggregates formed by hyperphosphorylation of a microtubule-associated protein known as tau, causing it to aggregate in an insoluble form. "Interestingly, Tau and CLU are in relation to neurofibrillary tangle, Tau is upregulated in the temporal cortex, and CLU is downregulated in the temporal cortex." (PMID 33952343, 2021).
non-alcoholic fatty liver disease (1 paper, 2019). "In the livers of non-alcoholic fatty liver disease mice fed a high-fat diet for one year, clusterin expression was higher than that in control mice." (PMID 31739636, 2019).
ovarian dysfunction (1 paper, 2024). The inability of the ovaries to function. "However, whether FBXW7 directly targets CCL2 and CLU to mediate ovarian dysfunction is still unclear." (PMID 39031722, 2024).
pancreatic adenocarcinoma (1 paper, 2012). "The results of the present study support the association of clusterin expression with lymph node metastasis and perineural invasion, and thus with aggressive tumor behavior of pancreatic adenocarcinoma." (PMID 22799602, 2012). "In the present study, we investigated relations between expression of the secretory isoform of clusterin and clinicopathologic parameters to assess its potential value as a prognostic indicator in pancreatic adenocarcinoma." (PMID 22799602, 2012). "In the present study, the authors investigated the expression of clusterin and its clinical significance in pancreatic adenocarcinoma." (PMID 22799602, 2012). "Immunoreactivity for clusterin was observed in 17 of the 52 (33%) pancreatic adenocarcinomas examined." (PMID 22799602, 2012). "Xie and colleagues recently reported associations between clusterin expression and various pancreatic pathologies including pancreas adenocarcinoma, and concluded that clusterin positivity is related to improved survival, at least by univariate analysis." (PMID 22799602, 2012). "Clusterin was expressed in 17 of the 52 (32.7%) pancreatic adenocarcinoma samples." (PMID 22799602, 2012). "To date, clusterin has not been found to be an independent prognostic factor for pancreatic adenocarcinoma." (PMID 22799602, 2012).
pancreatic ductal carcinoma (1 paper, 2020). "In addition, melittin treatment can significantly increase the exosomal long-chain non-coding RNA NONHSAT105177, down-regulate of the cholesterol metabolism genes, including clusterin (CLU), and inhibit pancreatic ductal carcinoma." (PMID 32746850, 2020).
pancreatic neuroendocrine tumor (1 paper, 2017). Pancreatic endocrine tumor, also known as pancreatic neuroendocrine tumor (PNET), describes a group of endocrine tumors originating in the pancreas that are usually indolent and benign, but may have the potential to be malignant. "Also, CLU is expressed in neuroendocrine cells in colon and pancreas, and is overexpressed in some gastric and pancreatic neuroendocrine tumors." (PMID 28902909, 2017).
pc (1 paper, 2021). "Clusterin does not reliably distinguish between LyP, pc-ALCL, and mycoses fungoides in large cell transformation, but it may be useful to discern pc-ALCL from some reactive cutaneous inflammatory conditions." (PMID 34572893, 2021).
peripheral nerve injury (1 paper, 2023). Injury to a peripheral nerve. "Among the four DE-SRGs identified by scRNA-seq, CLU has the potential to become a target for the development of drugs to inhibit astrocyte senescence in neuroinflammation following peripheral nerve injury." (PMID 37582709, 2023).
pituitary carcinomas (1 paper, 2011). A primary or metastatic malignant neoplasm affecting the pituitary gland. "In contrast, only modest clusterin expression was observed in non-tumorous pituitary glands and in GH/PRL- secreting tumors, while clusterin was undetectable in 76% of the very rarely encountered pituitary carcinomas." (PMID 21464964, 2011). "As nine of 12 pituitary carcinomas were devoid of clusterin expression, this protein may limit proliferation of benign adenomatous pituitary cells." (PMID 21464964, 2011). "As pituitary carcinomas are rarely treated with radiation or chemotherapy before surgery, we did not observe clusterin expression in human carcinoma specimens, as expected." (PMID 21464964, 2011).
pituitary tumor (1 paper, 2011). A benign or malignant neoplasm affecting the pituitary gland. "Based on the results presented here, we propose that in benign pituitary tumor cells of gonadotroph origin, the role of clusterin is to restrain proliferation." (PMID 21464964, 2011). "Concordantly, both the pre-tumorous αGSU.PTTG pituitary gland and pituitary tumors express high levels of clusterin, p15 and p16." (PMID 21464964, 2011). "Thus, clusterin-triggered p15 and p16 likely restrain pituitary cell proliferation in αGSU.PTTG pituitary tumors and in LβT2 gonadotroph-derived cells." (PMID 21464964, 2011). "Although only modest cytoplasmic clusterin, and intra-nuclear p15 and p16 expression were observed in WT murine pituitary glands, expression of these 3 proteins was enhanced in the transgenic pre-tumorous pituitary, and further induced in αGSU.PTTG pituitary tumors." (PMID 21464964, 2011).
placenta accreta (1 paper, 2021). The clinical condition in which any part of the placenta invades and is inseparable from the uterine wall. "In the present study, for the first time, a significant decrease in the expression level of the secretory form of clusterin was revealed in pregnant women with placenta accreta, increta, and percreta, compared to pregnant women with a scar on the uterus and/or placenta previa." (PMID 33805203, 2021).
polycystic liver disease (1 paper, 2021). "Up to now, no connection between polycystic liver disease and clusterin expression is known." (PMID 33798093, 2021).
primary biliary cholangitis (1 paper, 2025). Primary biliary cholangitis (PBC) is a chronic and slowly progressive cholestatic liver disease of autoimmune etiology characterized by injury of the intrahepatic bile ducts that may eventually lead to liver failure. "Clusterin was also elevated in liver sections from patients with primary biliary cholangitis, which showed an enhanced peritubular pattern in zone 1 hepatocytes and weak cytoplasmic expression in nonlesional parenchymal hepatocytes in patients with PBC." (PMID 40089787, 2025).
primary immunodeficiency (1 paper, 2023). "Additionally, immune-related Kyoto Encyclopedia of Genes and Genomes (KEGG) pathways, such as primary immunodeficiency and cytokine and cytokine receptor interaction, were activated with high CLU expression." (PMID 37686218, 2023).
proliferative diabetic retinopathy (1 paper, 2021). Advanced retinopathy due to diabetes mellitus characterized by the formation of new vessels in the retina. "On the other hand, proteomics analysis of vitreous and AH shows proteins that participate in a complementary system: clusterin, complement C3, and C4-A, which are factors that can serve as biomarkers for proliferative diabetic retinopathy (PDR)." (PMID 34575451, 2021).
proteinopathies (1 paper, 2020). "The differential abundance of clusterin in unrelated proteinopathies suggests that integration of clusterin in a blood-based exosome test could be of value in distinguishing PD patients from tau-related atypical parkinsonian syndromes." (PMID 32273329, 2020).
psoriatic arthritis (1 paper, 2024). Joint inflammation associated with psoriasis. "What important, to date, clusterin was among the top 30 proteins included in a panel of protein biomarkers with the potential to predict response to biological therapy in psoriatic arthritis." (PMID 39684771, 2024).
pterygium (1 paper, 2009). A wedge-shaped fibrovascular lesion arising from the bulbar conjunctiva and extending to the cornea. "The most abundant complementary DNAs from pterygium include clusterin, keratins 13 (Krt13) and 4 (Krt4), S100A9/calgranulin B, and spermidine/spermine N1-acetyltransferase (SAT1)." (PMID 19956562, 2009).
rectal cancer (1 paper, 2021). A primary or metastatic malignant neoplasm that affects the rectum. "Through Spearman correlation analysis, the association of BRCA1, CLU, AGTR1, and KL expression with the CNA value was estimated across rectal cancer." (PMID 35083278, 2021). "This study also evaluated the correlation of BRCA1, CLU, AGTR1, and KL expression with methylation levels in rectal cancer." (PMID 35083278, 2021). "Through the cBioPortal tool, we evaluated CNAs of BRCA1, CLU, AGTR1, and KL across rectal cancer." (PMID 35083278, 2021).
retinal disease (1 paper, 2016). "Our findings indicate for the first time that Clusterin in VH is associated with retinal disease like RVO." (PMID 27362861, 2016).
retinal vein occlusion (1 paper, 2023). An occlusion of the retinal vein. "Proteins that were upregulated in our study and in experimental retinal vein occlusion included fibronectin, annexin A1, galectin-3, alpha-crystallin B chain, vimentin, annexin A2, STAT1, GFAP, osteopontin, vitronectin, and clusterin." (PMID 37175625, 2023).